IL13 (interleukin 13)
Diseases named in the same sentence as IL13 in open-access papers (continued):
Sharing a sentence is not in itself a finding about the gene and the disease.
infection (continued). "In accordance with the reduced bacterial burden, we found decreased CXCL1 levels, lower numbers of infiltrating monocytes, and less pronounced lung infiltrates at 48 hr post-infection in Il13−/− as compared to WT animals." (PMID 28228256, 2017). "Nasal IL-5 and IL-13 levels were generally < 1 pg/ml in healthy controls, but higher at > 1 pg/ml in most stable allergic asthmatics prior to infection." (PMID 28373098, 2017). "The levels of Il4 and Il13 were elevated after infection in the NaS1 KO and wild-type mice compared to naïve mice." (PMID 28192541, 2017). "Our current data now show that Th2 cell-expressed AREG in an autocrine fashion facilitates the IL-33-induced expression of IL-13 at the site of infection." (PMID 29045902, 2017). "H. polygyrus larvae are particularly sensitive to IL-13-induced effector mechanism from day 7 until day 9 post infection, when they leave the gut mucosa in order to reside in the intestinal lumen." (PMID 29045902, 2017). "Fluke infection also upregulated IL-4 expression at 28 dpi (P = 0.0028), whereas IL-13 significantly increased at 28 dpi (P = 0.0259) and 70 dpi (P = 0.0426), peaking at 98 dpi (P < 0.0001)." (PMID 29216911, 2017). "We have previously reported that bronchial levels of IL-5 and IL-13 were greater during infection in asthmatic compared with healthy subjects." (PMID 28373098, 2017). "Reduced phosphorylation of STAT-3 was also observed in the presence of PD98059, an ERK inhibitor, indicating an involvement of pERK 1/2 in STAT-3 phosphorylation in addition to IL-13-JAK-2 axis during infection." (PMID 27826299, 2016). "With regards to immune profiles, patent infections of S. mansoni were strongly associated with young and adolescent cohorts, elevated SEA-specific IgG4, and systemic IL-6, IL-10 and IL-13." (PMID 27152725, 2016). "Secondary infection induced a rapid increase in the expression of IL-4, IL-6 and IL-13 from 2 wpsi and beyond." (PMID 27658962, 2016). "Consistent with the increased susceptibility to infection, we observed a significant increase in gene expression of the TH1 cell-associated cytokine Ifng in the intestine of VP-treated mice, even though Il13 levels were equal." (PMID 27598373, 2016). "WT, IL-4/IL-13-/- mice and IL-4Rα-/- mice were infected with N. brasiliensis and, at 5 days post-infection, SP-D levels in BAL fluid and serum were quantified." (PMID 26900854, 2016). "Mice were infected with 1.0 × 106 or 9.0 × 105 PFU of 12/11-19 or 12/12-6, respectively, and the number of ILCs and IL-13+ ILC2s was determined at day 4 after infection." (PMID 27156176, 2016). "Infection of hMDMs with L. donovani parasites generated a similar response like that of THP-1 MDMs by inducing a time-dependent increase in IL-13." (PMID 27826299, 2016). "Collectively, our study for the first time reveals a pro-parasitic role of host Bcl-2 and the capacity of host-derived IL-13 to modulate NO levels during infection via Bcl-2." (PMID 27826299, 2016). "Further, we detected equal worm burdens and Ifng and Il13 expression between infected Setd7f/f and Setd7ΔIEC mice at day 12 post infection." (PMID 27598373, 2016). "IL-13 was increased 100-fold during primary infection, but was undetectable in secondary infection (P<0.05)." (PMID 27467505, 2016). "Immunity to N. brasiliensis results in enhanced host secretion of IL-4 and IL-13, with IL-13 being essential for resolution of infection." (PMID 26900854, 2016). "We identified a significant increase in the total lung IL-13 concentration and the number of IL-13+ ILC2s at day 4 after infection." (PMID 27156176, 2016). "Consistent with our results obtained with RSV strain 01/2-20, both 12/11-19 and 12/12-6 induced a significant expansion of total ILCs and IL-13+ ILC2s by day 4 after infection." (PMID 27156176, 2016). "Surprisingly, IL-13 in SDP reached peak value at day 33 after infection, compared to day 105 in RDP." (PMID 27830756, 2016).
infection (continued). "Infection-induced increase in IL-13 observed in vitro was also visible in the in vivo model where serum IL-13 levels were consistently higher in the infected animals." (PMID 27826299, 2016). "Among the well-known Th2 cytokines, the expression of IL6, IL10 and IL13 was upregulated by infection in both breeds." (PMID 27197554, 2016). "RSV induced a 3-fold increase in the number of IL-13–producing ILC2s at day 4 after infection, with a concurrent increase in total lung IL-13 levels." (PMID 27156176, 2016). "To determine the role of TSLP during RSV-induced ILC2 activation, we assayed the total number of ILCs and IL-13+ ILC2s in TSLPR KO mice at day 4 after infection." (PMID 27156176, 2016). "After an initial schistosome-induced production of the Th1 cytokine (IFN-γ), Th2 cytokines such as IL-4, IL-5 and IL-13 are generated in response to established infections." (PMID 27152725, 2016). "Of note, upregulation of Th2 cytokines IL10 and IL13 by infection was more profound in CHB than in CS." (PMID 27197554, 2016). "On the other hand, Th2-like cytokines such as IL-4, IL-5 and IL-13 are predominant in immune responses to the chronic phase of infection which induce alternative activation of MΦs and upregulate the ADCC response." (PMID 26578348, 2015). "The up-regulated expression of IL-4, IL-5, IL-10, and IL-13 showed Th2 cell predominance in immunopathological reactions at late infection phase in response to infection by A. cantonensis." (PMID 26070790, 2015). "The Th2 response drives resolution of infection, and IL-13 signalling through IL-4Rα is an important component of the protective response." (PMID 25629518, 2015). "Numbers of NK cells increased significantly in most GKO strains following infection with the mutant virus except for WT and IL-13−/−/IL-4Rα−/− mice." (PMID 25751266, 2015). "As infection progressed, the ratio of IL-13 to IFNγ expanded such that by 7 dpi, IL-13 was significantly greater than IFNγ in RSV-infected neonates." (PMID 26438053, 2015). "Macrophages, eosinophils and lymphocytes gathered at the site of inflammation and Th2-type cytokine secretion such as IL-4, IL-5, IL-10, and IL-13 were increased under the stimulation of worm antigen in the late infection phase." (PMID 26070790, 2015). "FI-RSV-immunized mice on day 3 post-infection exhibited a significant (p<0.01) reduction in both IL-4 and IL-13 protein amounts in the lung." (PMID 25769044, 2015). "We note that IL-12 and IFNγ (a Th1 cytokine response), and IL-10, IL-4, IL-13 or IL-5 (Th2 cytokine response) were either down-regulated during the latter phase of infection or remained unchanged." (PMID 25719526, 2015). "The expression levels of TGF-β1 and IL-13 in S. japonicum infected ICOSL KO mice were lower than those in S. japonicum infected WT mice at 12 weeks post-infection (P<0.05)." (PMID 25590646, 2015). "The production of anti-inflammatory cytokine, TGF-β1, and the classic pro-fibrotic cytokine IL-13 by whole spleen cells were measured following infection." (PMID 25590646, 2015). "Though not as robust as earlier timepoints, a second, additional increase in IL-13 was observed at 6 dpi of initial infection." (PMID 26473724, 2015). "Historically, low levels of T cell cytokines (IL-2, IL-3, IL-4, IL-5, IL-9, IL-13) have been observed in fatal human cases of infection with EBOV and in infection of NHPs with MARV." (PMID 26512687, 2015). "−1055T in the IL13 gene promoter (rs1800925) correlates with different rates of infection in Mali and Kenya." (PMID 26540410, 2015). "Nuocytes have been shown to mediate type 2 immunity during N. brasiliensis infection by producing IL-13 early during infection; thus, it would be interesting to determine their contributions to protective immunity during secondary infection." (PMID 24516382, 2014). "Data from the N. brasiliensis system furthermore suggest that numerically ILC2 cells comprise the major source of IL-13 following infection, out-numbering CD4+ T cells." (PMID 24942690, 2014).
infection (continued). "Th-1 cytokines such as IFN-γ, TNF-α, and IL-2 favor resistance to infection while IL-4, IL-10 and IL-13 mediate disease progression and parasite persistence." (PMID 25500571, 2014). "The Th2 cytokines IL-5 and IL-13 increased steadily from week 2 onwards; IL-4 was only increased late in infection." (PMID 25398130, 2014). "Infection of mice with Nippostrongylus brasiliensis triggers a host protective immune response characterised by increased production of Th2 cytokines IL-13 and IL-4, goblet cell hyperplasia eosinophilia and elevated levels of serum IgG1 and IgE." (PMID 24516382, 2014). "Significant Th2-type responsiveness was seen from week 7 of infection onwards, after the onset of oviposition, with IL-4 and IL-5 rising ahead of IL-13." (PMID 25398130, 2014). "Lymphocytes of S. Typhi-infected patients in convalescence stimulated with MP for 48 hours generated significantly higher IFN-γ, MIP-1β, TNF-β, IL-13, and IL-9 responses than lymphocytes of the same patients in the acute phase of infection." (PMID 24615129, 2014). "Parasitic enteric nematodes induce a type 2 immune response characterized by increased production of Th2 cytokines, IL-4 and IL-13, and recruitment of alternatively activated macrophages (M2) to the site of infection." (PMID 24465430, 2014). "BCG-stimulated splenocytes displayed notably low concentrations of TH2 (IL-4 and IL-13) cytokines in all infection groups." (PMID 24433309, 2014). "IL-13 driven Th2 immunity is indispensable for host protection against infection with the gastrointestinal nematode Nippostronglus brasiliensis." (PMID 24516382, 2014). "In our study, after infection with S. japonicum for three weeks, cytokines (such as IL-4, IL-5, IL-6, IL-13, TNF-α and GM-CSF) in the sera of M. fortis were significantly increased, whereas cytokine levels of the BALB/c mice were much lower (data not shown)." (PMID 24886088, 2014). "Here, we opted to focus on IL-6, a cytokine that can directly affect macrophages, exert a variety of pro-inflammatory effects, and which is produced along with IL-4+IL-13 following infection with helminth parasites." (PMID 24736635, 2014). "Total MLN cells re-stimulated with α-CD3 resulted in significantly reduced production of IL-13 by CD28−/− mice at day 9 post-infection and was similar at day 12 compared to wild-type mice, a cytokine crucial for worm clearance." (PMID 24516382, 2014). "Mice lacking CC16 demonstrated significantly higher concentrations of Th2 cytokines IL-5 and IL-13 in BALF for several days following the infection." (PMID 24735334, 2014). "IL-4 cytokine levels peaked with the onset of microfilaremia at 60 dpi, whereas IL-5, IL-13 and IL-25 levels increased with the duration of infection." (PMID 24663956, 2014). "Only IL-1β, IL-6, TNF and IL-4 were significantly induced by infection in the spleen (the latter also in the liver), while the production of IL-12p70 and IL-13 decreased with infection, in the liver." (PMID 23459556, 2013). "Here, the significantly higher intestinal worm burden at day 5 secondary infection in IL-13−/− mice compared to IL-4−/− mice, demonstrated IL-13 signalling through IL-4Rα is essential for immunity against re-infection with N. brasiliensis." (PMID 24204255, 2013). "In agreement with this, immunization by repeated infection and sub-curative treatment led to high levels of IL-5, IL-10, IL-12, IL-13, IFN-γ, and TNF compared to uninfected mice, where levels were very low or undetectable." (PMID 24180253, 2013). "On day 14 days post infection the key Th2 cytokines IL-4 and IL-13 as well as anti-inflammatory IL-10 were produced in significantly higher amounts by mLN cells from infected mice in response to mitogen and parasite antigen." (PMID 24040152, 2013). "Strikingly, as early as 3 days post-infection, we observed a significant increase in production of the Th2 cytokine IL-13, which was still elevated at 7 days post-infection." (PMID 24098124, 2013).
infection (continued). "As both control mice and Itgb8 (CD11c-Cre) mice did not display production of IL-4 early during T. muris infection, these mice allowed us to test the role of the enhanced IL-13 response seen early during infection in Itgb8 (CD11c-Cre) mice." (PMID 24098124, 2013). "After REV infection, the expression levels of Th2 and regulatory cytokines (IL-4、IL-10 and IL-13) were drastically increased after 7 dpi, and moderately increased at 14 days and then up-regulated after 21 and 28 days following infection." (PMID 24358317, 2013). "In the current study, it was found that infection of BALB/c mice with P. berghei K173 caused marked increases in plasma levels of pro- and anti-inflammatory cytokines including IL-5, IL-10, IL-12, IL-13, IFN - γ, and TNF." (PMID 24180253, 2013). "Preliminary investigation into the role of IL-13 found that the presence of this cytokine can influence the outcome of infection." (PMID 23166721, 2012). "The low but significant increase in Ang4 expression seen in goblet cells of SCID mice post-infection points to the presence of innate cellular sources of IL-13." (PMID 22970115, 2012). "For example, segregation analysis of a Brazilian population has revealed that susceptibility to infection is controlled by the SM1 (S. mansoni 1) gene locus that has been linked to the 5q31–q33 chromosome region comprising the genes for IL-4, IL-5, and IL-13." (PMID 22545160, 2012). "Using IL-4- and IL-13-reporter mice to track these cells, a dominant IL-13-producing, innate cell population (nuocytes) expanded in response to the infection, similar to that seen after injection of IL-25 or IL-33." (PMID 22360486, 2012). "Further investigation into the early immune response to infection of Peyer’s patches suggests a role for IL-13 in the attenution of the ΔpmrF mutant strain." (PMID 23166721, 2012). "The high levels of serum IL-10 and IL-13 in the patient with fatal HME compared to non fatal HME is consistent with our murine data where IL-10 peaks in the serum at later stages of lethal infection, which occurs before animals succumb to infection." (PMID 22607204, 2012). "After systemic infection with L. donovani, a relatively silent phase during the first ∼3 weeks of infection was followed by increased expression of IL-4, IL-10, IL-13, and IL-21." (PMID 22275864, 2012). "The Ara4N-deficient S. Typhimurium was nearly as virulent as WT S. Typhimurium during infection of IL-13 KO mice, but was significantly attenuated in BALB/c mice." (PMID 23166721, 2012). "Th2-mediated differentiation of progenitor eosinophils (i.e. resident eosinophils), modulated by IL5 and IL13, also played an important role in helminth reduction in single infection, as indicated by the perturbation results." (PMID 22253585, 2012). "Consistent with this, intestinal gene expression levels of Il4, Il5 and Il13 at day 14 post-infection were heightened in CD103−/− mice." (PMID 21573179, 2011). "Th2 cytokines such as IL-4 and IL-13 are strongly up-regulated during a primary infection while TNFα and IFN-γ remains largely unchanged." (PMID 21414188, 2011). "Infection also induced significant but low level increases in NTHi-induced IL-5, IL-13, IL-17 and IL-22, and higher levels of IFN-γ release from mediastinal lymph nodes (MLN) cultures after 5 days, which returned to baseline levels after 26 days." (PMID 21998577, 2011). "We have recently shown a role for IL-13 and IL-10 in determining disease progression in the murine model of L.(V).panamensis infection." (PMID 21695103, 2011). "Thesupernatants from 4x infected mice were particularly rich in Th2-type cytokines, andover the first 4 days after infection contained 3- to 5-fold increased levels of IL-4and IL-13 compared to 1x mice, as well as significantly greater quantities of IL-10." (PMID 21445234, 2011). "The role of IL-13 in infection is typically attributed to its function as a Th2 cytokine, often acting as an immunological ‘switch’ by downregulating the Th1 response." (PMID 21573182, 2011).
infection (continued). "IL-13 is also produced by innate immune cells but the role of this cytokine in innate host defence against infection has received little attention." (PMID 21573182, 2011). "Confluent monolayers of LA4 cells were infected with Cmu and cells were treated with anti-IL-13 (αIL-13) mAb prior to and during infection." (PMID 21573182, 2011). "WT mice displayed increased symptoms, Cmu load and airway inflammatory cell burden after infection compared to their IL-13−/− counterparts." (PMID 21573182, 2011). "Cmu infection early in life leads to increased production of IL-13 following allergen challenge in adult mice." (PMID 21573182, 2011). "Quantitative real-time PCR of lung tissue RNA was used to measure the expression of IL-13 in WT mice following i.n. infection and normalised to uninfected controls." (PMID 21573182, 2011). "Both of these studies focus on the adaptive immune response to infection and attribute the ratio of Th2 cell derived IL-13 to Th1 cell IFN-γ as a key factor in determining the ability to mount a protective immune response and elimination of the pathogen." (PMID 21573182, 2011). "In the present study we demonstrate that early production of IL-13 during the innate immune response plays a critical and previously unrecognised role in promoting Cmu infection of the respiratory and genital tract." (PMID 21573182, 2011). "Further studies are required to identify the key cell(s) that are the early cellular sources of IL-13 during Cmu infection." (PMID 21573182, 2011). "To determine if IL-13 also played a role in promoting infection at other mucosal surfaces we intravaginally infected mice with Cmu and assessed disease severity and bacterial numbers over time." (PMID 21573182, 2011). "Infection was accompanied by a 5-fold increase in IL-13 expression, which was observed as early as 24 hours p.i. compared to naïve controls." (PMID 21573182, 2011). "IL-13 is a potent cytokine and low levels in the airway enhances infection and induces profound changes in lung physiology." (PMID 21573182, 2011). "The limited studies that have investigated the role of IL-13 in pathogen infection have focused on this molecule as a cytokine that is produced by activated CD4+ Th2 cells." (PMID 21573182, 2011). "It is therefore, feasible that the observed up-regulation of TFF3 is a response to IL-4 and IL-13 production or mucosal damage following infection." (PMID 21385411, 2011). "For example, acute infection of C57BL/6 mice with a high dose (200 eggs) of Trichuris results in a polarized Th2 cell response, characterized by high levels of IL-4, IL-5 and IL-13, and resistance to infection." (PMID 21573179, 2011). "By 1 hr post H37Rv-infection there was a significant decrease (P<0.001) in the concentration of the cytokines; Rantes, GM-CSF, Eotaxin IL-13, IL-9 and IL-1b." (PMID 22039457, 2011). "By contrast, IL-13−/− mice had significantly lower levels of Cmu at day 3 p.i. and throughout the course of infection." (PMID 21573182, 2011). "This is despite total BALF macrophage numbers being similar (data not shown) and Cmu numbers increased in the lungs of WT compared to IL-13−/− mice at this stage of infection." (PMID 21573182, 2011). "Goblet cell hyperplasia, which is IL-13-dependent, is also a prominent response to a primary infection in resistant strains of mouse." (PMID 19968992, 2010). "Infection of macrophages by primary R5X4 and X4 isolates of HIV-1 is inhibited by IL-4 and IL-13, an effect that is associated with down-regulation of surface CXCR4, CCR5 and CD4 expression." (PMID 20380696, 2010). "After H strain infection, the expression levels of IL-4, IL-13 and IL-10 in the bursa of chickens were up-regulated and peaked at 3 dpi and then declined at 5 dpi." (PMID 21143846, 2010). "Shortly after the beginning of egg deposition, a strong egg-specific Th2 response develops characterized by high levels of IL-4, IL-5, and IL-13 which decreases when the infection enters the chronic stage." (PMID 20537152, 2010).